RPS7 (ribosomal protein S7)
Description:
Component of the small ribosomal subunit. The ribosome is a large ribonucleoprotein complex responsible for the synthesis of proteins in the cell. Required for rRNA maturation. Part of the small subunit (SSU) processome, first precursor of the small eukaryotic ribosomal subunit. During the assembly of the SSU processome in the nucleolus, many ribosome biogenesis factors, an RNA chaperone and ribosomal proteins associate with the nascent pre-rRNA and work in concert to generate RNA folding, modifications, rearrangements and cleavage as well as targeted degradation of pre-ribosomal RNA by the RNA exosome.
Synonyms: S7; eS7; DBA8
Tractability: Small molecule: an approved drug acts on it; a structure with a bound ligand is known; a high-quality ligand is known. PROTAC: UniProt records ubiquitination sites on it; ubiquitination databases record sites on it; its protein half-life has been measured; a small molecule that binds it is known. Other modalities: a drug acting on it is in phase 2 or 3 trials.
Target class: Other cytosolic protein
Gene: Protein-coding gene on chromosome 2 (3,575,198 to 3,580,952, forward strand). Ensembl gene ENSG00000171863.
Subcellular location: Cytoplasm, cytoskeleton, microtubule organizing center, centrosome; Cytoplasm; Nucleus, nucleolus
Subcellular location (Human Protein Atlas): Cytosol; Endoplasmic reticulum
Pathways (Reactome):
Metabolism of proteins: Eukaryotic Translation Termination; Formation of a pool of free 40S subunits; Formation of the ternary complex, and subsequently, the 43S complex; GTP hydrolysis and joining of the 60S ribosomal subunit; L13a-mediated translational silencing of Ceruloplasmin expression; PELO:HBS1L and ABCE1 dissociate a ribosome on a non-stop mRNA; Peptide chain elongation; Ribosomal scanning and start codon recognition; SRP-dependent cotranslational protein targeting to membrane; Translation initiation complex formation; ZNF598 and the Ribosome-associated Quality Trigger (RQT) complex dissociate a ribosome stalled on a no-go mRNA
Metabolism of RNA: Major pathway of rRNA processing in the nucleolus and cytosol; Nonsense Mediated Decay (NMD) enhanced by the Exon Junction Complex (EJC); Nonsense Mediated Decay (NMD) independent of the Exon Junction Complex (EJC); rRNA modification in the nucleus and cytosol
Disease: SARS-CoV-1 modulates host translation machinery; SARS-CoV-2 modulates host translation machinery; Viral mRNA Translation
Cellular responses to stimuli: Response of EIF2AK4 (GCN2) to amino acid deficiency
Developmental Biology: Regulation of expression of SLITs and ROBOs
Metabolism: Selenocysteine synthesis
Gene Ontology:
Molecular function: mRNA 3'-UTR binding; mRNA 5'-UTR binding; protein binding; protein kinase binding; RNA binding; structural constituent of ribosome; ubiquitin ligase inhibitor activity
Biological process: negative regulation of ubiquitin-dependent protein catabolic process; ribosomal small subunit biogenesis; rRNA processing; cytoplasmic translation; translation
Cellular component: centrosome; cytoplasm; cytosol; cytosolic ribosome; cytosolic small ribosomal subunit; focal adhesion; membrane; nucleolus; nucleus; protein-containing complex; ribonucleoprotein complex; ribosome; small-subunit processome; nucleoplasm; synapse
Genetic constraint (gnomAD): Loss-of-function variants: 1 observed, 14.97 expected, observed/expected ratio (o/e) 0.0668, 90% interval 0.023 to 0.32. The upper end of that interval is the gene's LOEUF score, 0.32, which puts it in group 1 of 6, group 1 being the genes least tolerant of losing a copy. Missense variants: 117 observed, 188.1 expected, observed/expected ratio (o/e) 0.62, 90% interval 0.53 to 0.73. Synonymous variants: 68 observed, 72.16 expected, observed/expected ratio (o/e) 0.94, 90% interval 0.77 to 1.15.
Homologues: Orthologues: chimpanzee RPS7 (100% identical), guinea pig RPS7 (100% identical), macaque RPS7 (100% identical), mouse Rps7 (100% identical), pig RPS7 (100% identical), tropical clawed frog rps7 (98% identical), zebrafish rps7 (96% identical), Drosophila melanogaster RpS7 (72% identical), Caenorhabditis elegans rps-7 (59% identical).
Diseases named in the same sentence as RPS7 in open-access papers:
RPS7 is named in the same sentence as 48 diseases in open-access papers, as found by Europe PMC text mining. Sharing a sentence is not in itself a finding about the gene and the disease. The quoted sentences say what the papers report.
Diamond-Blackfan anemia (13 papers, 2011 to 2025). A congenital aregenerative and often macrocytic anemia with erythroblastopenia. "Previous studies have demonstrated that RPS7 mutation is strongly correlated with Diamond-Blackfan Anemia; however, more and more researches have recently focused on the effect of RPS7 in tumors." (PMID 38326908, 2024). "RPS7, 17, 19 and 29 are all associated with Diamond-Blackfan anemia, which is principally characterized by defects in bone marrow, craniofacial and limb development." (PMID 27784267, 2016). "Here we report the first two mouse mutations (Rps7Mtu and Rps7Zma) of ribosomal protein S7 (Rps7), a gene that has been implicated in Diamond-Blackfan anemia." (PMID 23382688, 2013). "The mutations of RPS7 have been shown to be associated with Diamond-Blackfan Anemia (DBA)." (PMID 26735579, 2016). "For instance, studies in Diamond-Blackfan anemia (DBA) demonstrated that mutations in 60S or 40S ribosomal proteins [such as RPL5, RPL11, RPS7, RPS10 among others] decrease the ribosome levels but leave the composition of the ribosomes intact." (PMID 30697227, 2018). "In Diamond-Blackfan Anemia, loss-of-function in RPL5, L11 or L26, or RPS7, S17, S19, or S26 is associated with Cathie facies, short stature, and upper limb, heart, and urogenital anomalies." (PMID 28046103, 2017). "In humans, mutations in RPs have been implicated in hematopoetic disorders, most notably Diamond-Blackfan anemia (DBA), which has been attributed to mutations in RPS19, RPS26, RPS24, RPS17, RPS10, RPS7, RPL35a, RPL26, RPL11, and RPL5." (PMID 23382688, 2013). "Mutation of human RPS7 has been implicated in Diamond-Blackfan anemia (DBA), yet the murine alleles do not present an analogous phenotype." (PMID 23382688, 2013). "The most well characterized is Diamond Blackfan anemia (DBA), which results from haploinsufficiencies in several different RP genes (RPS24/eS24, RPS17/eS17, RPL35A/eL33, RPL5/uL18, RPL11/uL5, RPS7/eS7, RPL36/eL36, RPS15/uS19, RPS27A/eS31) and RPS19/eS19, which is mutated in 25% of patients." (PMID 33565275, 2021).
colorectal cancer (6 papers, 2011 to 2025). A primary or metastatic malignant neoplasm that affects the colon or rectum. "Overall, we reveal that RPS7 inhibits colorectal cancer glycolysis through HIF-1α-associated signaling and may be a promising biomarker for prognosis prediction and a potential target for therapeutic treatment." (PMID 26735579, 2016). "In the following study it has been shown that it inhibits colorectal cancer cell glycolysis, it has also been found that RPS7 gene regulates cell apoptosis and cell cycle." (PMID 39140365, 2024). "We further performed the glucose uptake and lactate production, and colony formation assays to demonstrate the anti-RPS7 effect of HIF-1α on the growth of colorectal cancer cells." (PMID 26735579, 2016). "Clinically, the tissue microarray (TMA) analysis discloses the negative regulatory association between RPS7 and HIF-1α in colorectal cancer." (PMID 26735579, 2016). "In vivo assays also demonstrate that RPS7 suppresses colorectal cancer tumorigenesis and glycolysis." (PMID 26735579, 2016). "Meanwhile, overexpression of RPS7 in colorectal cancer tissues predicts good overall survival and progression-free survival, but high expression level of HIF-1α indicates poor overall survival and progression-free survival." (PMID 26735579, 2016). "In this study, we demonstrate that RPS7 inhibits the colorectal cancer (CRC) cell glycolysis by suppressing the expression of hypoxia-inducible transcription factor-1α (HIF-1α) and the metabolic promoting proteins glucose transporter 4 (GLUT4) and lactate dehydrogenase B (LDHB)." (PMID 26735579, 2016). "Not only in colorectal cancer (COAD), but RPS7, RPL8 and RPL30 also have higher expression in tumour tissues in various tumours, such as Thymoma (THYM) and large B‐cell Lymphoma (DLBC)." (PMID 40770837, 2025). "We performed IHC and scored the results in TMA consisting of 79 patients with stage I-III colorectal cancer and corresponding adjacent normal tissues (ANT) to test the expression status of RPS7, HIF-1α, GLUT4 and LDHB." (PMID 26735579, 2016). "RPS7 may inhibit glycolysis through HIF-1α-related signaling and thus play a protective role in colorectal cancer." (PMID 36518216, 2022). "Moreover, we showed that the high expression of RPS7 and low-expression of HIF-1α were significantly associated with good progression-free and/or overall survivals in stage IV CRC patients, which may be used as potential markers for diagnosis and clinical treatment of advanced colorectal cancer." (PMID 26735579, 2016). "It is possible that HNRNPL, PABPC1, RPS4X, and RPS7 correlate with oxaliplatin resistance but are not directly involved biochemically in the process of resistance in colorectal cancer cell types." (PMID 22118625, 2011). "Inactivation of tumor suppressor genes such as RPS7, MRPL39, MRPS23, ME2, and NDUFB9 were diagnosed with the development of many cancer types such as colorectal cancer, gastric cancer, breast cancer, and pancreatic cancer, but loss of these genes may be responsible for the development of GBM." (PMID 31137733, 2019). "Taken together, our data revealed the negative correlation between RPS7 and HIF-1α, and they modulate the glycolysis of colorectal cancer through molecules including GLUT4 and LDHB, which may represent novel prognostic markers and/or therapeutic targets for colorectal cancer." (PMID 26735579, 2016).
ovarian carcinoma (5 papers, 2011 to 2024). A malignant neoplasm originating from the surface ovarian epithelium. "In this study, we found that the aberrant expression of RPS7 might be associated with the development of ovarian cancer." (PMID 24244431, 2013). "Small ribosomal protein subunit S7 (RPS7) has been reported to be associated with various malignancies, but the role of RPS7 in ovarian cancer remains unclear." (PMID 24244431, 2013). "In ovarian cancer, shRNA-mediated knock down of RPS7 accelerated tumor cell proliferation and silencing of RPL41, which is 13.3-fold down-regulated in Huh6 cells on CAM, leads to anchorage-independent growth of fibroblasts and accelerated tumor growth in mice." (PMID 29662633, 2018). "To investigate the function of RPS7 in human ovarian cancer, we first detected the expression level of RPS7 in four human ovarian cancer cell lines and one immortalized human ovarian surface epithelial cell line (T29)." (PMID 24244431, 2013). "In this study, we found that silencing of RPS7 by a specific shRNA promoted ovarian cancer cell proliferation, accelerated cell cycle progression, and slightly reduced cell apoptosis and response to cisplatin treatment." (PMID 24244431, 2013). "Both E-cadherin and β-catenin were decreased in all ovarian cancer cell lines whose RPS7 was silenced." (PMID 24244431, 2013). "Based on these results, RPS7 appears to influence ovarian cancer cell invasion and migration possibly through regulation of MMP2, E-cadherin, and β-catenin." (PMID 24244431, 2013). "To elucidate the biological function of RPS7 in ovarian cancer, we silenced the expression of RPS7 by specific shRNA in ovarian cancer cell lines and tested the effects of RPS7 on cell proliferation, apoptosis, cell cycle, migration, invasion, and tumorigenesis." (PMID 24244431, 2013). "We also showed that silencing of RPS7 enhanced ovarian cancer cell migration and invasion." (PMID 24244431, 2013). "However, the clinical significance of RPS7 in ovarian cancer remains to be investigated in future." (PMID 24244431, 2013). "Thus, RPS7 may be used as a potential marker for diagnosis and treatment of ovarian cancer." (PMID 24244431, 2013). "Based on microarray studies of different cell lines, the proteins HNRPL, PABPC1, RPS4X, RPS7, and RALY are overexpressed in ovarian cancer cells resistant to oxaliplatin." (PMID 22118625, 2011). "The phosphorylation of P38 (Thr180/Tyr182) was reduced in all three ovarian cancer cell lines after RPS7 was silenced, but P38 was not changed in SKOV3-shRPS7, OVCA429-shRPS7 and OVCA433-shRPS7 cells." (PMID 24244431, 2013). "Although the basal levels of ERK1/2, MEK1/2, and P38 were inconsistently altered in ovarian cancer cells, the phosphorylated forms of MEK1/2 (Ser217/221), ERK1/2 (Thr202/Tyr204), JNK1/2 (Thr183/Tyr185), and P38 (Thr180/Tyr182) were consistently reduced after RPS7 was silenced." (PMID 24244431, 2013).
lung adenocarcinoma (4 papers, 2021 to 2024). A carcinoma that arises from the lung and is characterized by the presence of malignant glandular epithelial cells. "SMYD2 regulates the occurrence and metastasis of RPS7-mediated lung adenocarcinoma, representing itself as a potential prognostic biomarker and therapeutic target." (PMID 36816359, 2023). "Additionally, the downregulation of SMYD2 controls the metastasis of lung adenocarcinoma through the regulation of ribosomal protein S7 (RPS7) expression." (PMID 39482529, 2024).
lung carcinoma (4 papers, 2015 to 2024). "Therefore, the mechanism underlying SMYD2-mediated RPS7-driven lung cancer growth will need to be further explored in subsequent studies." (PMID 33935284, 2021). "Meanwhile, the role of SMYD2/RPS7 signaling pathway in lung cancer was analyzed." (PMID 35432530, 2022). "This study investigated whether the inhibitory effect of Baicalein on lung cancer cells was related to the SMYD2/RPS7 signaling pathway." (PMID 35432530, 2022).
breast carcinoma (3 papers, 2019 to 2024). "RPS7 functions as a tumor suppressor in colorectal cancer and ovarian tumors, whereas it acts as a pro-oncogenic factor in prostate cancer, lung adenocarcinoma and breast cancer." (PMID 38326908, 2024).
hepatocellular carcinoma (3 papers, 2024). A malignant tumor that arises from hepatocytes. "RBP RPS7 binds to the 3′ UTR of LOXL2 mRNA and stabilizes it, further promoting hepatocellular carcinoma metastasis, which can perform as a prognostic biomarker for hepatocellular carcinoma patients." (PMID 39510185, 2024).
prostate carcinoma (3 papers, 2019 to 2024). A carcinoma that arises from epithelial cells of the prostate gland. "Upregulation of RPS7 was correlated with worse recurrence-free survival and OS in patients with prostate cancer and overexpression of RPS7 dramatically increased prostate cancer cell growth." (PMID 33935284, 2021).
anemia (2 papers, 2013 to 2017). A reduction in the number of red blood cells, the amount of hemoglobin, and/or the volume of packed red blood cells. "Conversely, Rps7 mouse mutants show no anemia or hyperpigmentation, phenotypes associated with mutation of human RPS7 and other murine RPs, respectively." (PMID 23382688, 2013). "While modeling the pre-rRNA processing defect of an RPS7 DBA patient, these Rps7 mutant mice do not replicate the characteristic DBA phenotype of severe anemia." (PMID 23382688, 2013).
liver cancer (2 papers, 2024 to 2025). An epithelial or non-epithelial malignant neoplasm that arises from the liver. "Ribosomal protein S7 (RPS7) promotes liver cancer cell adhesion, migration, invasion capabilities, and metastasis." (PMID 40271197, 2025).
microphthalmia (2 papers, 2013 to 2022). Congenital or developmental anomaly in which the eyeballs are abnormally small. "Watkins-Chow and others have shown that Rps7-mutated mice develop uveal coloboma and microphthalmia." (PMID 35281111, 2022). "Frequent microphthalmia and uveal coloboma were also observed as features of the Rps7 mutant phenotype." (PMID 23382688, 2013).
COVID-19 (1 paper, 2022). A disease caused by infection with severe acute respiratory syndrome coronavirus 2. "However, whether RPS7 is specifically overexpressed in patients with COVID-19 with a high risk of thrombosis remains to be determined." (PMID 35692833, 2022). "In this study, six co-upregulated genes, RPS7, IGF1R, DICER1, ERH, MCTS1, and TNPO1, and two co-downregulated genes, FLNA and PXN, were identified from COVID-19 and thrombosis datasets." (PMID 35692833, 2022). "Based on bioinformatics analysis and previous studies, this study identified hub genes (RPS7, IGF1R, DICER1, ERH, MCTS1, TNPO1, FLNA, and PXN) that may contribute to the evaluation and treatment of COVID-19 and thrombosis." (PMID 35692833, 2022).
depression (1 paper, 2023). "Although few studies have reported the relationship between RPS7 and myocardial infarction or depression, other members of the ribosomal protein family, such as P70S6K, have been reported to be significantly down-regulated in both myocardial infarction and depression mice." (PMID 37547246, 2023).
glaucoma (1 paper, 2016). Increased pressure in the eyeball due to obstruction of the outflow of aqueous humor.
lymphoma (1 paper, 2013). A malignant (clonal) proliferation of B- lymphocytes or T- lymphocytes which involves the lymph nodes, bone marrow and/or extranodal sites. "The relative mRNA expression levels of 4 ribosomal protein genes that were up-regulated in CUP (RPS7, RPL11, RPS10, and RPL36) were compared with the levels in normal lymphoma and 24 known cancer types." (PMID 23671674, 2013).
malaria (1 paper, 2007). Malaria is a serious and sometimes fatal disease caused by a parasite that commonly infects a certain type of mosquito which feeds on humans. "The ribosomal proteins S4 (RpS4) and S7 (RpS7) were used as internal controls for infection studies of ONNV and the malaria parasite, Plasmodium berghei, respectively." (PMID 17625007, 2007).
microcephaly (1 paper, 2013). A congenital or acquired developmental disorder in which the circumference of the head is smaller than normal for the person's age and sex. "Interestingly, the neuronal phenotypes in mouse Rps7 mutants correlate with the report of microcephaly as one of 11 congenital craniofacial anomalies that can be associated with DBA, and are consistent with RP mutant phenotypes observed in different model organisms." (PMID 23382688, 2013).
non-small cell lung carcinoma (1 paper, 2022). A group of at least three distinct histological types of lung cancer, including non-small cell squamous cell carcinoma, adenocarcinoma, and large cell carcinoma. "Signaling pathway regulation studies showed that Baicalein also inhibited the SMYD2/RPS7 signaling pathway in human non-small-cell lung cancer cells." (PMID 35432530, 2022).
ovarian tumor (1 paper, 2013). "In conclusion, we demonstrate that RPS7 inhibits ovarian tumor growth and metastasis through regulation of the PI3K/AKT and MAPK signal pathways." (PMID 24244431, 2013).
pulmonary hypertension (1 paper, 2022). Increased pressure within the pulmonary circulation due to lung or heart disorder. "To further investigate the relationships among the SRP-DGs and risk of SSc-PH, we constructed a nomogram model using seven SRP-DGs (RPL32, RPS12, RPS14, RPS23, RPS3, RPS7, and SRP9) to predict the risk of pulmonary hypertension complications in patients with SSc." (PMID 36518216, 2022).
red cell aplasia (1 paper, 2013). "Because human RPS7 mutations are associated with DBA, a disease characterized by red cell aplasia, we undertook an initial characterization of circulating blood in adult Rps7Mtu/+ mice (on a C3H/He background) and Rps7Zma/+ mice (on a mixed C57BL/6J; BALB/cJ background)." (PMID 23382688, 2013).